IGF1 (insulin like growth factor 1)
Diseases named in the same sentence as IGF1 in open-access papers (continued):
Sharing a sentence is not in itself a finding about the gene and the disease.
lung carcinoma (continued). "Previous studies on various cancers, including lung cancer, have emphasised the local synthesis and regulation of IGF-1 in cancer tissues." (PMID 34177367, 2021). "Recent studies have demonstrated the possible potential molecular pathways for SPHK1 and HAS2 in cancer progression, one of which is that SPHK1 induces lung cancer cell migration and paclitaxel resistance by modulating IGF-1-induced EMT." (PMID 33506044, 2021). "IGF1 was considered to be a key factor in the carcinogenesis of some tumors, including colon cancer, esophageal cancer, and lung cancer." (PMID 33298061, 2020). "It is known that some tumors, especially squamous cell carcinoma in lung cancer, produce high levels of IGF-1 themselves." (PMID 30679643, 2019). "To clarify this issue, we examined the involvement of SphK1 in IGF-1-induced EMT using human lung cancer cell line A549, and its paclitaxel-resistant subline." (PMID 31413745, 2019). "Clinical trials have been finished or just begun to investigate the safety and efficacy of antibodies against IGF-1 signaling in lung cancer." (PMID 30018981, 2018). "Abnormal IGF-1/IGF-1R signaling has been extensively studied in lung cancer that mediates oncogenesis, progression, metastasis, resistance to chemotherapy, or tyrosine kinase inhibitors (TKIs)." (PMID 30018981, 2018). "The role of IGF-1/IGF-1R signaling abnormalities in lung cancer has been extensively reviewed elsewhere." (PMID 30018981, 2018). "We examined the involvement of PKM2 on the proliferation of NCI-H1299 lung cancer cells in response to IGF-1, given that high IGF-1 serum levels have been reported as a risk factor for lung cancer." (PMID 27340866, 2016). "miR-486 can directly target components of insulin-like growth factor (IGF) signaling, including IGF1, and functions as a potent tumor suppressor of lung cancer both in vitro and in vivo." (PMID 25793394, 2015). "In lung cancer, miR-486 regulates the insulin growth factor signaling pathway by targeting insulin-like growth factor 1 (IGF1), IGF1 receptor (IGF1R), and phosphoinositide-3-kinase, regulatory subunit 1 (alpha) (PIK3R1)." (PMID 26966540, 2015). "MSC conditioned medium favored lung cancer cell proliferation and lung cancer cells stimulated the expression of IL-6, IGF-1, VEGF and DKK1 on MSCs." (PMID 26582222, 2015). "Conversely, the tumor suppressor miR-486 directly targets the components of insulin growth factor (IGF) signaling, including IGF-1, IGF-1R, and p85a, in lung cancer." (PMID 24816813, 2014). "Based on these efforts, the phosphatidylinositol-3-kinase (PI3K)/protein kinase B (AKT) pathway and the IGF1/IGF1R signaling pathway have emerged as potential determinants of radiation resistance in human lung cancer cells." (PMID 25344917, 2014). "In our previous study, results demonstrated that the new anti-aging gene klotho was crucial for the proliferation and apoptosis of lung cancer cells (A549 cells), mainly through inhibiting the IGF-1/R pathway." (PMID 23437382, 2013). "Epidemiological studies have shown that high IGF-1 and low IGFBP-3 levels are independently associated with a high risk of common cancers, including lung cancer." (PMID 24339922, 2013). "Furthermore, the ability of CR to regulate IGF-1 levels and the Insulin/IGF-1 pathway could also be responsible for its anti-tumor effect as an elevated IGF-1 serum level is associated with an increased risk of breast, prostate, colon, and lung cancer in humans." (PMID 22934068, 2012). "The pooled results of the meta-analysis didn’t show evidence of the relationship between the circulating concentrations of IGF-1 and IGFBP-3 and lung cancer risk in the nested case-control studies." (PMID 23185474, 2012). "After adjusting for the effect of pack-years smoked, exposure to cooking fumes, and family history of lung cancer, we selected the IGF1 X/X genotype carriers as the reference group for all green tea drinkers." (PMID 22347413, 2012).
lung carcinoma (continued). "The joint effect of cumulative smoking dose with IGF1 (CA)n repeat, IGF2 820, IGFBP3 -202 genotypes for lung cancer risk." (PMID 22347413, 2012). "Subsequently, we analyzed the joint effect of cumulative smoking dose with IGF1, IGF2, and IGFBP3 genotypes on lung cancer risk after adjusting for the effect of green tea consumption, exposure to cooking fumes, and family history of lung cancer." (PMID 22347413, 2012). "Pooled measure was calculated as the inverse variance-weighted mean of the natural logarithm of multivariate adjusted OR with 95% CIs for highest vs. lowest levels to assess the association of circulating IGF-1 and IGFBP-3 concentrations and lung cancer." (PMID 23185474, 2012). "IGF-1 has been documented to perform strong mitogenic and anti-apoptotic effects both in normal and cancerous cells, including lung cancer cell lines." (PMID 23185474, 2012). "In this study, we evaluated the effects of smoking, green tea consumption, as well as IGF1, IGF2, and IGFBP3 polymorphisms, on lung cancer risk." (PMID 22347413, 2012). "Here, we evaluated the effects of smoking, green tea consumption, and IGF1, IGF2, and IGFBP3 genotypes on lung cancer risk." (PMID 22347413, 2012). "And PI3K/Akt signaling pathway is also involved in IGF-1-induced VEGF-C expression in lung carcinoma cells." (PMID 22496919, 2012). "Thus, tea polyphenols may decrease lung cancer risk by lowering IGF1 levels." (PMID 22347413, 2012). "Adding a layer of complexity, since insulin and IGF-1 half-receptors have been reported to form heterodimers with members of the EGFR family in lung cancer, this adds another layer of complexity in assessing TKI-mediated resistance." (PMID 24212944, 2011). "Multiple lines of evidence suggest the involvement of the IGF-1/insulin pathways across a range of malignancies, including both NSCLC and small cell lung cancer (SCLC), and inhibition of IGF-1 signaling pathway is a potential therapy for human lung cancer." (PMID 20642846, 2010). "Ample clinical and laboratory data indicate a critical role for insulin/IGF-1 signaling in lung cancer." (PMID 20642846, 2010). "We studied the effect of klotho on IGF-1 pathway activation in A549 lung cancer cells, which express high levels of IGF-1R and show an enhanced proliferation following IGF-1 treatment." (PMID 20642846, 2010). "It is widely accepted that klotho inhibits the activation of the IGF-1 pathway, which has an important function in lung cancer tumorigenesis, and IGF-1 induces A549 cells proliferation." (PMID 20642846, 2010). "An aetiological role for IGF-1 and IGFBP-3 in malignancy is supported by clinical studies that associate high IGF-1 and low IGFBP-3 levels with increased risk of several cancers, such as breast, colorectum, and lung cancer." (PMID 19570255, 2002). "IFGBP3 overexpression may induce lung cancer cell apoptosis and increase cisplatin sensitivity by suppressing IGF1 signaling." (PMID 36164607, 2022). "Prior studies have elucidated that IGF-1 is elevated in patients with lung cancer, suggesting that elevated circulating insulin may play a role in lung cancer." (PMID 36048786, 2022). "The IGF-1 levels, which are expected to be higher in lung cancer patients, may decrease in the patient groups due to age; thus, age may be a confounding factor." (PMID 34177367, 2021). "In breast and lung cancer cell lines, lycopene was able to reduce the level of IGF-1 and increase the level of IGF binding proteins (IGFBPs), which could sequestrate IGF." (PMID 34948455, 2021). "The usage of IGF-1-based agents urges for more researches in developmental disorders and inflammatory lung diseases, as current data are generally collected from limited number of animal experiments and are less exuberant than those in lung cancer." (PMID 30018981, 2018).
lung carcinoma (continued). "Insulin-like growth factor 1 (IGF1) was found to initiate self-renewal of lung cancer stem cells in dormant lung tumors via the activation of a PI3K/Akt/β-catenin pathway and production of the angiogenic factors chemokine (C-X-C motif) ligand 1 (CXCL1) and placental growth factor (PlGF)." (PMID 30603045, 2018). "Previous epidemiological studies have indicated that insulin-like growth factor 1 (IGF-1) might play an important role in the development of breast, colorectal, and lung cancer." (PMID 28949980, 2017). "High levels of circulating IGF-1 may increase lung cancer risk, while high levels of IGFBP-3 may reduce the risk of lung cancer." (PMID 28885346, 2017). "Lastly, using the RNAi-resistant Trop2 cDNA as a template, we constructed Trop2 mutants harboring a deletion in either the EGF-like or thyroglobulin type-1 domains present in the extracellular region, both of which are required by Trop2 to bind IGF-1 in lung cancer cells." (PMID 25238142, 2014). "Our results suggest that TM4SF4 overexpression in lung carcinoma cells results in resistance to radiotherapy via IGF1-induced IGF1R activation and blocking the activity of TM4SF4 using specific antibody can be a promising therapeutics against TM4SF4-overexpressing lung adenocarcinoma." (PMID 25344917, 2014). "Klotho could also inhibit proliferation and increase apoptosis of human lung cancer A549 cells, which may be partly due to the inhibition of IGF-1/insulin pathways and involving regulating the expression of the apoptosis-related genes bax/bcl-2." (PMID 23516476, 2013). "Heavy smokers carrying susceptible IGF1, IGF2, and IGFBP3 have a higher risk of lung cancer." (PMID 22347413, 2012). "With respect to the circulating IGF-1 concentration and lung cancer risk, initial meta-analysis has shown that it was at no significantly increased risk with the OR of 1.047(95% CI:[0.802,1.367], P = 0.736) for the highest vs. lowest levels of IGF-1." (PMID 23185474, 2012). "Concerning the relationship of circulating IGFBP-3 concentration and lung cancer risk, the pooled OR 0.960 (95%CI:[0.591,1.559], P = 0.868) as well as to SMD −0.097 (95%CI:[ −0.264,0.071], P = 0.258) were calculated similar to that of IGF-1." (PMID 23185474, 2012). "A requirement for the IGF-1 receptor in mediating lung cancer growth is consistent with other reports that IGF-1 stimulates rapid anchorage-independent growth in vitro, while IGF-1R inhibition slows tumor growth in both animal xenograft studies and human clinical trials." (PMID 21699731, 2011). "There was no indication of an association between IGF-1 and lung cancer (OR=1.02 (0.80–1.31)) nor between IGFBP-3 and lung cancer (OR=0.98 (0.61–1.58))." (PMID 16804529, 2006). "However, the IGF-1 signaling was involved in virtually all stages of lung cancers." (PMID 36936149, 2023). "First, the information on the grade of asthma, COPD, and lung cancers was not available, so we cannot examine whether the association with IGF-1 was different based on these characteristics." (PMID 36936149, 2023). "The usage of IGF-1-based therapeutic agents urges for more researches in developmental disorders and inflammatory lung diseases, as the majority of current data are collected from limited number of animal experiments and are generally less exuberant than those in lung cancer." (PMID 30018981, 2018). "Finally, we analyzed human lung adenocarcinoma gene expression in lung cancer patients to determine whether IGF-1 expression can predict patient outcomes." (PMID 29255466, 2017). "Thus, until now, there is little evidence for a link between IGF‐1 and lung cancer risk, but an inverse association between IGFBP‐3 and lung cancer risk has been observed." (PMID 27734632, 2016).
lung carcinoma (continued). "Lung cancer in acromegalic patients seems to be rare; and it's seems like there is not an increase prevalence of non-small cell cancer in acromegalic patients compared to normal population according to several studies even if high level of IGF1 value increase proliferation of lung cells." (PMID 22891085, 2012). "However, IGF1, IGF2, and IGFBP3 may be susceptibility genes for lung cancer only in certain ethnic populations." (PMID 22347413, 2012). "However, the test for interaction between cumulative smoking dose and IGF1 genotypes on lung cancer risk was not significant." (PMID 22347413, 2012). "Macrophage IGF-1 may thus have a pathological role in lung cancer." (PMID 21699731, 2011). "In summary, klotho, a potential tumor suppressor, can inhibit the growth of lung cancer cells A549 and promote their apoptosis, this may be partly due to the inhibition of IGF-1/insulin pathways and involving regulating the expression of the apoptosis-related genes bax/bcl-2." (PMID 20642846, 2010). "IGF-1R, an RTK activated by IGF-1 and IGF-2, contributes to lung cancer by initiating pathways involved in cell proliferation and survival." (PMID 38540176, 2024). "Analysis of the predictive efficacy of postoperative 1dCRP, IL-6, IGF-1, and IGF-3 combined methods in predicting secondary lung infection in elderly patients after lung cancer surgery." (PMID 39495987, 2024). "IGF-1 and fibroblast growth factor -1 (FGF-1) can synergistically promote the expansion of lung cancer stem cells (LCSCs) and significantly down regulate the apoptotic signals through the activation of MAPK signaling pathway." (PMID 36329881, 2022). "Our findings are in line with a previous study demonstrating that activated KRAS proto-oncogene and insulin-like growth factor 1 signaling induce MDM4 expression at least partially via ELK1 in breast, colon, and lung cancer cells." (PMID 33429878, 2021). "The IGF-Trap significantly reduces metastatic spread of colon and lung carcinoma cells to the liver, representing a novel promising alterative to IGF1R or IGF1/IGF2 antibodies." (PMID 34440844, 2021). "In this study, the IGF-1, IGFBP-4, and PAPP-A levels were analysed in samples from patients with different lung cancer types and stages to evaluate their potential use as lung cancer biomarkers." (PMID 34177367, 2021). "By targeting IGF1, IGF1R and PIK3R1 this miRNA induces cell cycle arrest and reduces migration of lung cancer cells while acting as a tumour suppressor in a xenograft mouse model." (PMID 34547721, 2021). "proved that the increasing secretion of IGF-1 and CCL20 promotes brain metastasis of lung cancer cells by polarizing microglia and suppressing innate immune function." (PMID 34804946, 2021). "In the context of lung cancer, amphiregulin has been shown to inhibit cell apoptosis in NSCLC cell lines via insulin-like growth factor-1 (IGF1)-dependent mechanism." (PMID 31438559, 2019). "In this study, we explored the role of SphK1 in IGF-1-induced EMT, migration and paclitaxel resistance of the human lung cancer cell line A549." (PMID 31413745, 2019). "It has been revealed that in osteosarcoma, gynecological, gastrointestinal, proste and lung cancers, the increasing level of IGF-1 and changes of IGF-1 signaling pathway are frequently noticed." (PMID 30679643, 2019). "IGFBP4 is generally considered to have a negative regulatory role on IGF-1, for example, both IGFBP4 and IGFBP2 were found to be down-regulated through promoter hypermethylation in lung carcinomas." (PMID 28443133, 2017). "Treatment of TM4SF4-overexpressing lung carcinoma cells with anti-TM4SF4 antibody suppressed cell growth, which was mediated by suppression of IGF1 expression." (PMID 25344917, 2014). "In these lung cancer cells, TM4SF4 overexpression increased the expression of IGF1, a ligand that activates IGF1R, which appears to be a key event in activation of the IGF1R pathway." (PMID 25344917, 2014).
lung carcinoma (continued). "Insulin-like growth factors (IGFs), IGF1 and IGF2 are peptide hormones with strong mitogenic effect on both normal and cancerous cells, including lung cancer." (PMID 22347413, 2012). "Efforts have been made expecting to prove the clinical significance of circulating IGF-1 and IGFBP-3 in cancers by evidence-based methods, among which lung cancer is a magnificent being." (PMID 23185474, 2012). "Standard mean difference (SMD) was also calculated to indicate the difference of the circulating IGF-1 and IGFBP-3 concentrations between the lung cancer case group and the control group." (PMID 23185474, 2012). "In this study we evaluated differences among healthy subjects and subjects suffering from lung cancer in the 24-hour secretory profile of melatonin, cortisol, TRH, TSH, FT4, GH, IGF-1 and IL-2 and circadian variations of lymphocyte subpopulations." (PMID 20565977, 2010). "Numerous studies have indicated that the levels of IGF-1 and IGF-2 are increased in the tumor tissues of lung cancer, and these growth factors promote cell growth, proliferation, invasion, and apoptosis suppression by activating multiple signaling pathway, including PI3K/Akt and Ras/MAPK." (PMID 40741172, 2025). "For example, CAFs can over‐secret ANXA2, which triggers EMT in lung cancer cells; this pro‐EMT phenotype is dependent on the secretion of hepatocyte growth factor (HGF) and insulin‐like growth factor 1 (IGF1) by CAFs, thus facilitating the cancer cells' evasion of EGFR targeting." (PMID 40162549, 2025). "In preclinical models of melanoma and lung cancer, elevated expression of insulin-like growth factor 1 (IGF-1) and the chemokine CXCL12/SDF-1 by non-irradiated CAFs have been shown to be responsible for radioprotective effects on cancer cells." (PMID 37170098, 2023). "IGF-1 and IGF-2 are mitogenic peptides in various cells, including those of lung cancer." (PMID 36902237, 2023). "It has been reported that insulin-like growth factor 1 (IGF-1), the ligand of the IGF-1 receptor (IGF-1R), is highly expressed in the TME of the liver metastasis, and the signaling from IGF-1R promotes the tolerance to osimertinib in EGFR-positive lung cancer." (PMID 36140210, 2022). "A recent study also showed that IGF1, the adult-type IGF sharing the same IGF axis signaling with IGF2, is responsible for the initiation of lung cancer recurrence by inducing self-renewal and clonal expansion of cancer stem cells and results in subsequent neoangiogenesis and recurrence." (PMID 34539876, 2021). "In lung cancer, miR-135a induces apoptosis and inhibits invasion and angiogenesis by binding to the 3′-UTR of insulin-like growth factor 1 (IGF-1) mRNA and inactivating the IGF-1/PI3K/AKT signaling pathway." (PMID 32944391, 2020). "The insulin-like growth factor (IGF) system, involving two hormones of IGF-1 and IGF-2, two receptors to these two hormones (IGF-1R and IGF-2R), and several binding proteins (IGFBP1-7), plays an important role in the development of lung cancer." (PMID 31354621, 2019). "It is possible that both IGF‐1 and IGFBP‐3 contribute to the development of lung cancer." (PMID 27734632, 2016). "A nonsignificant increase in IGF1 level was also observed with anamorelin vs placebo in the murine lung cancer study." (PMID 27552970, 2016). "IGF-1 alone does not promote lung cancer cell proliferation (data not shown), however IGF-1 induced PC-9 and H460 cells showed decreased sensitivity to EGFR-TKIs compared to parental cells." (PMID 26554308, 2015). "We also evaluated the effect of IGF1, IGF2, and IGFBP3 (data not shown) on lung cancer risk by green tea consumption." (PMID 22347413, 2012). "While alveolar macrophages are an important component of the chronic inflammatory milieu responsible for promoting lung tumorigenesis, IGF-1 has not been examined as a possible connection between macrophage recruitment and lung cancer progression." (PMID 21699731, 2011).